ANG (angiogenin)
Diseases named in the same sentence as ANG in open-access papers (continued):
Sharing a sentence is not in itself a finding about the gene and the disease.
glioma (15 papers, 2012 to 2023). A benign or malignant brain and spinal cord tumor that arises from glial cells (astrocytes, oligodendrocytes, ependymal cells). "In whole-grade gliomas, patients with higher-ANG expression in their tumors were significantly associated with shorter OS." (PMID 37928479, 2023). "This study aimed to investigate the molecular and clinical characterization of ANG expression at transcriptome level and the association with glioma-related immune response." (PMID 37928479, 2023). "Based on these studies, we emphasized the vital role of ANG in all grades of gliomas and proposed the profound association between ANG and glioma-related immune response, which further extended the results of their studies." (PMID 37928479, 2023). "The results agreed very well across the three datasets and showed that ANG expression in higher-grade gliomas was significantly higher than the expression in lower-grade gliomas, preliminarily suggesting an association of ANG with malignancy." (PMID 37928479, 2023). "Secondly, IDH-wildtype gliomas showed a significantly higher ANG expression than those harboring IDH mutation in all datasets, further confirming the involvement of ANG in aggressiveness." (PMID 37928479, 2023). "Given the profound associations with distinct genomic alterations, ANG is supposed to play crucial roles in glioma genesis, progression, microenvironment remodeling, and drug resistance, further confirming its robust correlation with higher malignancy of gliomas." (PMID 37928479, 2023). "To investigate the molecular characterization of ANG expression in whole-grade gliomas, we first obtained and analyzed Chinese Glioma Genome Atlas (CGGA) 301 dataset (CGGA301), including mRNA microarray data of 301 samples of whole-grade gliomas." (PMID 37928479, 2023). "Only one previous study described the association between clinicopathological factors and ANG expression in patients with GBM, accounting for approximately 30–40% of all gliomas." (PMID 37928479, 2023). "Among these six genes, ANG, IL1A, LOXL1, LOXL2, and STEAP3 played risk roles in the survival of glioma patients (HR > 1), while F5 was a potential protective factor (HR < 1)." (PMID 37891828, 2023). "This study represents the first integrative report describing the clinical and molecular characterization of ANG in whole-grade glioma patients." (PMID 37928479, 2023). "Meanwhile, overexpression of ANG was more inclined to recruit monocyte–macrophage lineage cells and dendritic cells into the glioma TME, further validating what we found in GSVA." (PMID 37928479, 2023). "To confirm that ANG expression was also up-regulated at the protein level, we performed IHC staining for ANG on a glioma TMA." (PMID 37928479, 2023). "F‐MWNT‐ANG exhibited enhanced uptake in the glioma brain compared to the non‐targeted conjugate, demonstrating the potential of ANG‐conjugated f‐MWNTs for effective drug delivery to brain malignancies." (PMID 35593206, 2022). "A high expression of angiogenin has been described in different types of cancers and to their malignant transformation, including gliomas that are brain tumours fast-growing, aggressive and with a poor prognosis." (PMID 31500197, 2019). "For example, extracellular 5′-tRNA fragments (5′-tRFs, 30–32 nt-long), also called 5′-tRNA halves (tiRNAs), are produced in glioma cells by ribonuclease known as angiogenin (ANG)." (PMID 30585246, 2018). "Finally, Kaplan–Meier plots demonstrated that higher expression of ANG was significantly correlated with shorter survival in gliomas." (PMID 37928479, 2023). "ANG expression was significantly higher in state 1 and state 2, suggesting that ANG was more upregulated in early-stage tumor cells and was highly and selectively expressed in a particular branch of mature glioma cells." (PMID 37928479, 2023).
glioma (continued). "An interaction between angiogenin and fibulin-1 could provide one possible mechanism behind the increased proliferation we observed when glioma cells were grown on matrix generated by hypoxic astrocytes." (PMID 33802060, 2021). "VEGF is known as the most crucial angiogenin during angiogenesis in glioma." (PMID 32116702, 2020). "Therefore, VEGF modulates neuronal health and nerve repair; and exogenous angiogenin delivery can be considered a promising tool of anti-angiogenic therapy for treating gliomas, where malignancy is highly related to angiogenesis." (PMID 31500197, 2019). "Finally, CBD determined a decrease in the potential angiogenic factor Angiogenin, whose increase significantly correlates with the higher grade of glioma malignancy." (PMID 24204703, 2013). "Vascular endothelin‐2 (Angiopep‐2, ANG) peptide from the aprotinin Kunitz domain can specifically target brain cells and bind to low‐density lipoprotein receptor‐associated protein‐1 (LRP1) to achieve targeted delivery, which is overexpressed in the BBB and glioma." (PMID 35593206, 2022). "In our study, ANG was comprehensively analyzed in both LGG and GBM based on three independent glioma cohorts, mainly highlighting the perspectives of the clinicopathological relationship and molecular characterization." (PMID 37928479, 2023). "The results showed that ANG, EXO1, FBXO17, IGF2BP3, and NSUN7 displayed distinctly higher expression levels in glioma compared to controls (p < 0.05)." (PMID 33634155, 2021). "Our data confirmed the up-regulation of ANG, EXO1, FBXO17, IGF2BP3, and NSUN7 in glioma than normal samples (all p < 0.0001)." (PMID 33634155, 2021). "To date, no comprehensive report has been published to demonstrate ANG expression in whole-WHO grade gliomas." (PMID 37928479, 2023). "Because the levels of vWF, MMP9, VCAM1, angiogenin, and HGF were increased in both GBM and MI patients, but not in the lower-grade gliomas, these factors seem to be necessary for neovascularization in general, both under reactive and high-grade neoplastic conditions." (PMID 31428150, 2019).
bladder cancer (14 papers, 2005 to 2025). "Elevated ANG expression has been linked to higher rates of invasive and higher-grade bladder cancers as well as worse clinical outcomes." (PMID 27317771, 2016). "Relative to control cases, a reduction in SDC1 and overexpression of MMP9, MMP10, SERPINE1, IL8, APOE, SERPINA1, ANG were associated with high stage bladder cancer." (PMID 25387487, 2014). "Therefore, an elevated plasma level of ANG may serve as a novel predictor for the risk of bladder carcinoma." (PMID 30828780, 2020). "Angiogenin, belonging to the ribonuclease A family, has been reported to enhance angiogenesis and metastatic progression in bladder cancer through the activation of critical downstream elements within the PI3K–AKT–mTOR pathway." (PMID 41179679, 2025). "Univariate analysis indicated age, race, MMP9, IL8, VEGFA, CA9, PAI1, ApoE, A1AT, ANG and MMP10 were associated with bladder cancer." (PMID 33823873, 2021). "The expression of seven of the 10 bladder cancer -associated diagnostic signature (MMP9, MMP10, PAI1, CA9, APOE, SDC1, and ANG) showed a positive association with bladder cancer diagnosis, while IL8 and A1AT showed a negative correlation with cancer diagnosis." (PMID 31905599, 2019). "The overexpression of MMP10 was associated with higher grade disease, while overexpression of MMP10, PAI1, SDC1 and ANG were associated with high stage bladder cancer and CA9 was associated with low stage bladder cancer." (PMID 31905599, 2019). "Our results indicate that the ANG gene is amplified in human bladder cancer, leading to reduced expression of DNMT3b and increased expression of MMP2." (PMID 27317771, 2016). "The results suggest that the MMP2 gene is amplified in ANG-overexpressing bladder cancer cells, supporting ANG's oncogenic characteristics." (PMID 27317771, 2016). "Angiogenin is upregulated by hypoxia in cell lines and is raised in the blood and tumours of patients with bladder cancer." (PMID 16052224, 2005). "ANG requirement for the cellular survival, proliferation and angiogenesis of ANG-overexpressing bladder cancer cells is in accordance with the oncogenic model in which the growth and survival of cancer cells can be suppressed by the inactivation of a single oncogene." (PMID 27317771, 2016). "Thus, it is tempting to speculate that the adverse expression of ANG-DNMT3b-MMP2 may be utilized as a prognostic factor for human bladder cancer." (PMID 27317771, 2016). "Thus, the survival analysis further suggests the ANG-DNMT3b-MMP2 axis play a role in bladder cancer progression and thus could hold promise as prognostic markers." (PMID 27317771, 2016). "We first analyzed ANG, DNMT3b and MMP2 mRNA levels in human bladder cancer tissues by quantitative RT-PCR." (PMID 27317771, 2016). "To further define the role of ANG, DNMT3b and MMP2 in tumorigenesis, we collected 78 fresh bladder cancer samples from bladder cancer patients and extracted DNA and RNA for analysis." (PMID 27317771, 2016). "In our analysis of a publicly available database, it was suggested that ANG and MMP2 genes are amplified in a subset of bladder cancers." (PMID 27317771, 2016). "Mean relative mRNA levels for both ANG and MMP2 in muscle invasive bladder cancer were significantly elevated compared to the mean relative mRNA levels for ANG and MMP2 in non-muscle invasive bladder cancer, thus confirming our results." (PMID 27317771, 2016). "Interestingly, expression of ANG, DNMT3b and MMP2 is correlated with disease free survival in human bladder cancer." (PMID 27317771, 2016). "In addition to these bladder cancer cell lines, MMP2 gene amplification may occur in bladder tumors with high ANG levels." (PMID 27317771, 2016). "Angiogenin (ANG) interacted with ribonuclease inhibitor and ANG up-regulation activated phosphorylation of key downstream target molecules of PI3K/AKT/mTOR signaling pathway, leading to the promotion of tumor angiogenesis, tumorigenesis and metastasis in bladder cancer cells." (PMID 26312564, 2015).
cardiac hypertrophy (14 papers, 2013 to 2025). "Pro-angiogenic factors such as vascular endothelial growth factor (VEGF), basic fibroblast growth factor, and ANG, are involved in the development of cardiac hypertrophy." (PMID 33041815, 2020).
lung carcinoma (14 papers, 2010 to 2026). "Pro-angiogenic activity of lung cancer has an important influence on the levels of angiogenin and VEGF." (PMID 23412843, 2012). "Median angiogenin serum concentration in patients with lung cancer was 286.94 ng/ml." (PMID 23412843, 2012). "The purpose of this study was to prospectively investigate the local concentrations of VEGF and angiogenin in the part of the lung, affected by a lung cancer and compare them by the healthy side of the lung and by the concentrations in the serum of patients with lung cancer." (PMID 23412843, 2012). "Stress-induced tiRNA cleavage by angiogenin (ANG) and tRF-Leu-CAG have been reported to promote colorectal cancer metastasis and the proliferation and cell cycle of lung cancer cells as tumor drivers." (PMID 34225773, 2021). "We found that digestive cancers have significant gene expression changes enriched in HIF-VEGF and ANG-TIE pathways, especially in colorectal, gastric, and intrahepatic cancers, while in reproductive cancers and lung cancer, most of the pathways are regulated." (PMID 28335793, 2017). "Angiogenin and VEGF concentrations in bronchial secretions from healthy and affected side of the lung show influence of lung cancer angiogenic activity and other conditions including co-morbidity." (PMID 23412843, 2012). "This prospective study evaluated expression of two central regulatory molecules: angiogenin and vascular endothelial growth factor (VEGF) in patients with lung cancer." (PMID 23412843, 2012). "We summarize that angiogenin and VEGF expression in systemic, background and local samples of patients with lung cancer are affected by different mechanisms." (PMID 23412843, 2012). "Angiogenin and VEGF concentrations in systemic, background and local samples of patients with lung cancer are affected by different mechanisms." (PMID 23412843, 2012). "The important role in serum angiogenin concentration has constitutional component in contrast to serum VEGF concentration, which is influenced by lung cancer." (PMID 23412843, 2012). "Concentrations of angiogenin and VEGF in bronchial secretions from the healthy side of the lung were in a correlation (p = 0.003) as well as angiogenin and VEGF concentrations from area affected with lung cancer (p < 0.001)." (PMID 23412843, 2012). "Concentrations of VEGF and angiogenin did not correlate for a particular molecule in any possible couple from three taken samples in patients with lung cancer." (PMID 23412843, 2012). "Therefore we assume that serum angiogenin concentration was not significantly affected by local conditions in the lung and in the lung cancer." (PMID 23412843, 2012). "The study showed that there is a strong local production of VEGF in lungs of patients with lung cancer and that VEGF serum concentration but not angiogenin concentration was in positive correlation with tumour size and with metastatic stage of disease." (PMID 23412843, 2012).
preeclampsia (14 papers, 2009 to 2026). Preeclampsia is a hypertensive disorder of pregnancy that is characterized by new-onset hypertension with proteinuria presenting after 20 weeks of gestation, and depending on mild or severe forms may initially present with severe headache, visual disturbances, and hyperreflexia. "Several altered proteins, including PAPPA and ANG, were linked to preeclampsia." (PMID 40974471, 2025). "A recent study has shown that inhibitors of angiogenin may contribute to the pathophysiology of preeclampsia." (PMID 40974471, 2025). "Investigating similar interactions for SAA4 and ANG may uncover new regulatory networks in CL function and preeclampsia." (PMID 40974471, 2025). "In preterm preeclampsia, PlGF and VEGFR-1 displayed a differential abundance in both soluble and EV fractions, whereas angiogenin, CD40L, endoglin, galectin-1, and TIMP1 were changed only in the soluble fraction." (PMID 41515555, 2025). "Additionally, SAA4, ANG, CFHR5, IGKV3-7, and PAPPA have been suggested to play a role in the context of preeclampsia." (PMID 40974471, 2025).
ischemic stroke (12 papers, 2013 to 2025). A stroke disorder caused by obstruction of blood flow to the brain, due to thrombotic (local blood clot formation) or embolic (due to a blood clot or other material traveling from another site) event. "In the present study, we have described the temporal profile of angiogenin from the subacute phase to the most chronic phases after ischemic stroke during rehabilitation." (PMID 30008694, 2018). "In this study, we have examined the role of angiogenin and EPCs during IRT in ischemic stroke patients and in a neurorehabilitation animal model after cerebral ischemia." (PMID 30008694, 2018).
colorectal cancer (11 papers, 2016 to 2025). A primary or metastatic malignant neoplasm that affects the colon or rectum. "In specific diseases like colorectal cancer, angiogenin (ANG) acts as a nuclear nuclease, elevating tRNA expression levels and cleaving the tRNA molecule into 5′ and 3′ ends, leading to an increase in tiRNA levels." (PMID 38596214, 2024). "NK cells from colorectal cancer patients are polarized toward a pro-angiogenic phenotype, and they express angiogenin, MMP2 and MMP9." (PMID 34638439, 2021). "Mechanically, the response process of 5’ tiRNA-His-GTG to the tumor hypoxic microenvironment, regulated by the HIF1α/ANG axis, reveals a specific pathway of 5’ tiRNA-His-GTG involved in colorectal cancer progression and provides clues for the design of new colorectal cancer therapeutic targets." (PMID 40726981, 2025).
diabetic nephropathy (11 papers, 2009 to 2025). "High angiogenin level induces excessive angiogenesis, which in turn may be responsible for diabetic nephropathy progression by causing enlargement of the glomerular filtration surface." (PMID 28634856, 2018). "In a model of diabetic nephropathy, urinary progenitor-secreted exosomes were found to reduce podocyte apoptosis by suppressing caspase-3 and promoting vascular regeneration, which may be related with the cytokines VEGF, TGF-β1, angiogenin and BMP-7 contained in urinary progenitor-derived exosomes." (PMID 33401654, 2021).
ischemia (11 papers, 2013 to 2024). A hypoperfusion of the BLOOD through an organ or tissue caused by a PATHOLOGIC CONSTRICTION or obstruction of its BLOOD VESSELS, or an absence of BLOOD CIRCULATION. "Substantial evidence has demonstrated that most tiRNAs are produced by angiogenin (ANG) under stress, such as ischemia, oxidative injury, ultraviolet exposure, arsenite exposure, or infection diseases." (PMID 36761955, 2023). "Only angiogenin and angiopoietin-2 were increased in MI patients compared to GBM patients, suggestive of their association with the acute onset of ischemia occurring in MI." (PMID 31428150, 2019). "Angiogenin was expressed in brain tissue homogenates 24 h after ischemia before rehabilitation, presenting a non-significant 3.5-fold increase in the ipsilateral vs. the contralateral hemisphere." (PMID 30008694, 2018).
myocardial infarction (11 papers, 2012 to 2025). Gross necrosis of the myocardium, as a result of interruption of the blood supply to the area, as in coronary thrombosis. "Under hypoxic conditions, AECs secrete higher human-origin proangiogenic cytokine levels, including angiogenin (ANG), EGF, interleukin (IL)-6, and monocyte chemoattractant protein (MCP)-1, contributing to myocardial tissue regeneration in a myocardial infarction rat model." (PMID 37711653, 2023).
Alzheimer disease (10 papers, 2013 to 2024). A progressive, neurodegenerative disease characterized by loss of function and death of nerve cells in several areas of the brain leading to loss of cognitive function such as memory and language. "Angiogenin (ANG) was suggested as a rare risk factor for Alzheimer’s disease (AD), Parkinson’s disease (PD), and ALS." (PMID 37566027, 2023). "For instance, elevated plasma levels of angiogenin and tissue inhibitors of matrix metalloproteinase-4 as well as VEGF have been identified as risk factors for the development of Alzheimer’s disease." (PMID 36293539, 2022). "Given that ANG mutations are causative of familial forms of ALS, PD and even Alzheimer's disease (Prehn and Jirström, 2020), defective action of ANG may be an underlying cause of impaired stress response and dysregulated tiRNA production." (PMID 39552337, 2024).
asthma (10 papers, 2012 to 2025). "Angiogenesis antibody arrays revealed that CM of BSMC from asthma patients contained significantly higher levels of angiogenin, ENA-78, GRO-α, IL-6, IL-8 and MCP-1." (PMID 24339939, 2013). "We found that in the presence of 5% FCS human BSMC of asthma patients released a different complement of angiogenic regulators including angiogenin, IL-6, MCP-1 and importantly three CXCR2 ligands, namely ENA-78, GRO-α and IL-8." (PMID 24339939, 2013). "Angiogenesis is a feature of airway remodeling in asthma, and it has been demonstrated that IL-33 can increase the expression of blood vessel von Willebrand factor (vWF), as well as angiogenic factors such as angiogenin when administered nasally to a murine asthma surrogate model." (PMID 31293586, 2019). "Furthermore, increased levels of angiogenin and monocyte chemotactic protein-1 (MCP-1) were also found in the airways and airway lining fluids (broncho alveolar lavage fluid, sputum) of asthma patients." (PMID 24339939, 2013).